CBL (Cbl proto-oncogene)
Diseases named in the same sentence as CBL in open-access papers (continued):
Sharing a sentence is not in itself a finding about the gene and the disease.
RASopathy (21 papers, 2016 to 2025). Developmental syndromes caused by germline mutations (or in rare cases by somatic mosaicism) in genes that alter the Ras subfamily and mitogen-activated protein kinases that control signal transduction. "Germline monoallelic CBL UbLOF variants underlie a disorder that resembles Noonan syndrome (NS), a RASopathy." (PMID 39403923, 2024). "Five unrelated probands have been identified with heterozygous missense variants in CBL and diagnosed with RASopathy accompanied with retina involvement." (PMID 37711606, 2023). "CBL syndrome is a RASopathy caused by heterozygous germline mutations of the Casitas B-lineage lymphoma (CBL) gene." (PMID 36123612, 2022). "The NGS panel identified a homozygous mutation in the CBL gene: Exon 9 c.1259G > C; p.Arg420Pro, known to be involved in RASopathy disorders." (PMID 35887217, 2022). "CBL syndrome [MIM 613563] is a RASopathy caused by heterozygous germline variants of the Casitas B-lineage lymphoma (CBL) gene [MIM 165360]." (PMID 36123612, 2022). "The CBL mutation is a known RASopathy-associated variant that activates MAPK signaling." (PMID 41309580, 2025). "NSLL is one of the last RASopathies identified and is classically associated with CBL variants." (PMID 40332000, 2025). "We show that spontaneous colony formation in CMML functionally covers NRAS and CBL, the most frequent RASopathy gene mutations (>10%), and thus may be considered as a functional parameter for RAS-pathway hyperactivation in these patients." (PMID 32842710, 2020). "Patients with RASopathies are known to be at increased risk of cancer development, CBL syndrome is associated with an increased risk of JMML and CBL mutations occurs in of a variety of myeloid neoplasms." (PMID 36123612, 2022). "Because of their functional significance RAS signaling pathway components including NRAS, KRAS, NF-1, PTPN11, and CBL were summarized as RASopathy genes within one category." (PMID 32344757, 2020). "For example, RASopathies, such asNoonan syndrome, Neurofibromatosis 1 and Leopard syndrome, are a subtype ofdevelopmental diseases characterized by mutations in genes encoding for components ofthe Ras/MAPK pathway (NF1, PTPN1, SOS1, RAF1,KRAS, NRAS, SHOC2, CBL)." (PMID 29719609, 2018). "Genes involved in the sutures of the cranial bones, microcephaly, closure of the neural tube (e.g., VANGLI1), and in RASopathy (e.g., BRAF and CBL) were also identified." (PMID 39458107, 2024). "BRAF, CBL, NF1, PTPN11, RAF1, SOS1 and SOS2 contain at least 20 phosphosites each, and they account for 326 of the phosphosites identified in RASopathy proteins (61% of the total)." (PMID 34229750, 2021).
lung carcinoma (19 papers, 2010 to 2025). "Among them, five new genes, including CBL, exhibited a significant association with the risk of developing lung cancer in both cross-tissue and lung tissue models." (PMID 39130630, 2024). "The reduced expression of c-CBL in human lung cancer tissue has been linked to the activation of c-Src/AKT signaling, increased cancer metastasis, and unfavorable patient survival." (PMID 39130630, 2024). "Somatic CBL mutations have been reported in lung cancers while diffuse teratomas and embryonal rhabdomyosarcoma have been observed in patients with germline CBL mutations resulting in LOH in the CBL locus." (PMID 35159106, 2022). "In the current study, immunoblotting and PamGene platforms were utilized to investigate the effective target genes of representative CBL Mts, S80N/H94Y double mutation, Q249E, V391I, and W802* in lung cancer." (PMID 28835699, 2017). "In this study, we show relatively high frequency of c-CBL mutations in lung cancers, especially in the large cell type among Caucasians and particularly among African-Americans." (PMID 20126411, 2010). "In this study, we report novel c-CBL somatic mutations S80N/H94Y, Q249E and W802* in Caucasian, Taiwanese and African-American lung cancer patients, respectively." (PMID 20126411, 2010). "In conclusion, the results presented in this study demonstrate that c-CBL is frequently mutated or even lost in lung cancers." (PMID 20126411, 2010). "In the present study, we have demonstrated the occurrence of c-CBL mutations in lung cancer patients, especially with different ancestral variations." (PMID 20126411, 2010). "Previously, we have shown somatic mutations in CBL in lung cancer." (PMID 27244893, 2017). "In lung cancer, mutations in CBL and in other driver genes usually co-occur." (PMID 25803323, 2015). "Given the critical role of CBL in normal homeostasis and cancer, we hypothesized that it might be mutated in lung cancers." (PMID 20126411, 2010). "Taking the overall mutation rate of c-CBL to be a combination as somatic missense mutation and LOH, it is clear that c-CBL is highly mutated in lung cancers and may play an essential role in lung tumorigenesis and metastasis." (PMID 20126411, 2010). "We have reported earlier c-CBL mutations in a small cohort of Taiwanese lung cancer samples." (PMID 20126411, 2010). "In lung cancers the relevant substrates of c-CBL in terms of degradation or signal transduction are yet to be identified." (PMID 20126411, 2010). "The fact that about 7% of lung tumor samples are likely to have c-CBL mutations and an additional 22% are likely to harbor c-CBL-related LOH, makes c-CBL a highly mutated molecule in lung cancer." (PMID 20126411, 2010). "We therefore propose c-CBL as an efficacious target for lung cancers in African-Americans that needs to be further substantiated." (PMID 20126411, 2010). "To investigate the role of c-CBL in lung cancer, we analyzed its genomic DNA in tumor and paired normal samples drawn from multiple ethnicities." (PMID 20126411, 2010). "Furthermore, the CBL protein has been found to promote the apoptotic effects of Shikonin by exerting a negative regulation on the PI3K/Akt signaling pathway in lung cancer cells." (PMID 39130630, 2024). "We thus hypothesize that c-CBL mutations might contribute to the oncogenic potential of MET and EGFR in lung cancer." (PMID 20126411, 2010). "The role CBL plays in lung cancer tumorigenesis remains unclear." (PMID 28835699, 2017). "Thus we tested the effect of c-CBL knockdown in lung cancer cells." (PMID 20126411, 2010). "In this study, we revealed a novel mechanism of BASP1 in promoting lung cancer malignancy: BASP1 enriches EGFR in lipid rafts and enhances EGFR signaling by reducing CBL-dependent EGFR ubiquitination." (PMID 33042262, 2020).
lung carcinoma (continued). "In our previous studies in lung cancer, the results not only showed the interation of c-CBL and MET but also showed knockdown c-CBL induced MET overexpression and became sensitive to MET inhibitors (data not shown)." (PMID 27244893, 2017). "Additionally, the expression levels of c-CBL and CBL-b were found to be upregulated, suggesting the involvement of CBL-mediated regulation of Akt and ERK signaling in the apoptosis induced by β-elemene in lung cancer cells." (PMID 39130630, 2024). "Compared to A549, H358 lung cancer cells express relatively high levels of endogenous c-CBL (data not shown)." (PMID 20126411, 2010). "Hence, in the current study, we sought to not only determine if MET is a target for CBL-mediated degradation and ubiquitination in NSCLC, and also whether it could serve as a novel therapeutic target in lung cancer." (PMID 28835699, 2017).
gastric cancer (18 papers, 2013 to 2025). A primary or metastatic malignant neoplasm involving the stomach. "Overall, these findings highlight the potential role of c-CBL in gastric cancer pathogenesis and provide insights into the dysregulation of c-CBL and its associated molecules in gastric cancer progression." (PMID 39130630, 2024). "Met-dependent loss of CBL protein in MET-amplified gastric cancer cell lines represents another mechanism contributing to signal dysregulation in gastric cancer." (PMID 27472394, 2016). "DR5, CBL-b/c-CBL, and TRAF2 form the complexes in TRAIL-resistant gastric cancer cells that target CBL-b and c-CBL by inhibiting the interaction of TRAF2 with caspase-8 and subsequent caspase-8 multiubiquitination." (PMID 39130630, 2024). "The results showed that the expression level of c-CBL in gastric cancer tissues was significantly lower compared to the adjacent normal tissues, with a low expression rate of 61.4% (27/44) in gastric cancer cases." (PMID 39130630, 2024). "Studies in the human gastric carcinoma cell line GTL‐16 cells demonstrated that prolonged HGF/SF‐MET signalling led to both multiubiquitination (proteasomal targeting) and K63‐linked polyubiquitination (lysosomal routing) of GAB1 in a CBL‐dependent manner." (PMID 40550626, 2025). "CBL protein provides a theoretical basis for the treatment of gastric cancer." (PMID 39130630, 2024). "Moreover, the overexpression of c-CBL, CBL-b, and EGFR exhibited a significant association with the invasion and progression of gastric cancer." (PMID 39130630, 2024). "Notably, the application of transforming growth factor α exhibited a substantial capacity to induce the expression of CBL protein within gastric cancer cells." (PMID 39130630, 2024). "Additionally, one study found that oxaliplatin combination treatment with TRAIL in gastric cancer cells enhances apoptotic signaling through casitas B-lineage lymphoma (CBL) regulation and death receptor redistribution into LRs." (PMID 34342264, 2021). "Consequently, CBL could emerge as a promising novel molecular marker for identifying invasive gastric cancer." (PMID 39130630, 2024). "Moreover, CBL is also reported as a tumor suppressor gene in gastric cancer." (PMID 35027542, 2022). "Its interactions with EGFR and c-CBL disrupt the normal degradation of EGFR, thus contributing to the enhanced EGFR signaling in gastric cancer cells." (PMID 39130630, 2024). "In this study, the immunohistochemical method was used to measure the expression levels of c-CBL, CBL-b, and EGFR in 124 gastric cancer tissue samples and 16 normal gastric mucosa samples." (PMID 39130630, 2024). "The findings revealed that the positive rates of c-CBL, CBL-b, and EGFR in the gastric cancer group were significantly higher compared to the normal group (71.0% vs. 18.0%)." (PMID 39130630, 2024). "CBL-b and c-CBL were found to interact with DR5, linking DR5 with TRAF2 and inducing ubiquitination of caspase-8 in TRAIL resistant gastric cancer cells." (PMID 38534365, 2024). "As revealed by these experiments, the inhibition of CBL plays a role in mediating ATO-induced apoptosis in NB4 cells and G2/M phase arrest in gastric cancer cells." (PMID 39130630, 2024). "Interestingly, CBL protein acts as a tumor suppressor in most cancers, such as non-small cell lung cancer, GBM, and gastric cancer." (PMID 35027542, 2022). "In contrast, expression of ITCH and CBL, the ubiquitin E3 ligases that have been shown to promote polyubiquitination and proteosomal degradation of c-FLIP25,26, are normal or increased in the same gastric cancer tissues 43–45." (PMID 29374180, 2018). "Similarly, MST1R had interactions with AKT, AKT1, and MST1, while LTR interacted with IRS1, CBL, PIK3C and SHC1, none of which have been found to be associated with gastric cancer before." (PMID 37287033, 2023).
gastric cancer (continued). "Expression of CBL is variable in different gastric cancer cell lines, whereas the expression of ITCH is increased in the same group of gastric cancer cell lines, suggesting that the ITCH-mediated and CBL-mediated c-FLIP degradation processes are not operational in gastric cancer." (PMID 29374180, 2018). "In summary, we identify DTX1, but not CBL or ITCH, as the E3 ligase regulating c-FLIP protein stability in gastric cancer cells." (PMID 29374180, 2018).
myeloproliferative neoplasm (18 papers, 2011 to 2025). A clonal hematopoietic stem cell disorder, characterized by proliferation in the bone marrow of one or more of the myeloid (i.e., granulocytic, erythroid, megakaryocytic, and mast cell) lineages. "Previous studies have shown that deletions or loss-of-function mutations in CBL are frequently observed in myeloid malignancies, especially in myelodysplastic syndrome/myeloproliferative neoplasm (MDS/MPN) overlap syndromes." (PMID 37317974, 2023). "CBL mutations are predominantly found in myelodysplastic syndrome/myeloproliferative neoplasms (MDS/MPN), where mutations are clustered within the LHR and RING domains with Tyr371 mutations as the major hotspot." (PMID 33627783, 2021). "Deregulation of CBL and its E3 activity is observed in myeloproliferative neoplasms and other cancers, including breast, colon, and prostate cancer." (PMID 33627783, 2021). "Here, we explore the oncogenic mechanism of E3-inactive CBL mutants identified in myeloproliferative neoplasms." (PMID 33627783, 2021). "Mutations clustered in the linker region or RING finger domain of CBL, and rarely CBL-B, which abrogate E3 activity, have been identified in a subset of patients with myelodysplastic syndrome/myeloproliferative neoplasms (MDS/MPN), chronic myelomonocytic leukemia or juvenile myelomonocytic leukemia." (PMID 27276677, 2016). "This first-reported case of SF3B1-mutated myelodysplastic/myeloproliferative neoplasm with thrombocytosis (MDS/MPN-SF3B1-T), harboring coexisting ASXL1, JAK2 p.R683G, and CBL mutations challenges conventional genomic prognostic paradigms." (PMID 40772034, 2025). "However, mutant CBL works as oncogene in myeloid leukemia and myeloproliferative neoplasms." (PMID 33231565, 2020). "Not surprisingly, CBL mutations have been reported in 10% of patients with MDS/myeloproliferative neoplasm (MPN) overlap syndrome and these patients display clinical features such as splenomegaly, monocytosis, and anemia." (PMID 34638574, 2021). "Here, using VAV1-Cre-induced conditional CBL/CBL-B double knockout (DKO) in mice, we established an animal model that exhibits a neonatal myeloproliferative disease (MPD)." (PMID 27449297, 2016).
myelodysplastic syndrome (16 papers, 2010 to 2023). A clonal hematopoietic disorder characterized by dysplasia and ineffective hematopoiesis in one or more of the hematopoietic cell lines. "Along these lines, recent work evaluating the role of gene mutations on the prognosis of myelodysplastic syndromes demonstrated that patients with mutations in KRAS or NF1 show worse OS than patients with NRAS or CBL mutations." (PMID 29259247, 2017). "Furthermore, CBL mutations could also be found in myelodysplastic syndromes, chronic myelogenous leukemia and other chronic myeloproliferative diseases." (PMID 35159106, 2022).
melanoma (15 papers, 2016 to 2026). A malignant, usually aggressive tumor composed of atypical, neoplastic melanocytes. "Higher percentages of BRAF, RAS, NF1, and CBL mutations were observed in patients with melanoma in the head and neck than in patients with melanoma in the other five sites." (PMID 37649078, 2023). "In addition, the casitas B-lineage lymphoma (c-CBL), an E3 ubiquitin ligase that was previously associated with acute myeloid leukemia, was found to be strongly expressed in human melanoma compared to benign melanocytic nevi." (PMID 33800394, 2021). "Only about 3 % of melanomas have shown c-CBL mutations as per TCGA data base." (PMID 27472394, 2016). "Therefore, we hypothesized that alterations of the FAK-SRC-GRB2 nexus might be associated with the effects of c-CBL knockdown on the potential of melanoma cells to proliferate, migrate and invade." (PMID 27472394, 2016). "We validated several such cis-regulatory interactions using CRISPR inhibition, providing evidence for known cancer driver genes MDM4 and CBL, as well as the SRY-box transcription factor SOX4, as likely melanoma risk genes." (PMID 39802764, 2024). "Proprion one (pro-PrP) is an adaptor protein for the E3 ligase c-CBL in human melanoma, allowing it to polyubiquitinate the activated insulin-like growth factor-1 receptor (IGF-1R), thus increasing melanoma metastasis." (PMID 39130630, 2024). "This highlights the significant role played by c-CBL in the proliferation, migration, and invasion of melanoma cells, as well as the inhibition of the FAK-GRB2-SRC interaction." (PMID 39130630, 2024). "A large number of studies have shown that CBL gene plays a crucial cancer-promoting role in immune regulation of primary melanoma and is closely related to the progression of metastatic disease." (PMID 39130630, 2024). "The results showed that knocking out c-CBL led to a decrease in proliferation, clonal survival, and the migration of melanoma cells." (PMID 39130630, 2024). "For CBL (locus 36, signal 44), two out of three gRNAs for one of four tested SNPs (rs61900794; melanoma and melanocyte enhancer, ATAC open in melanoma) showed small but significant effects on CBL transcription (0.81–0.84 fold expression relative to NTC1)." (PMID 39802764, 2024). "The expression of c-CBL, both at the mRNA and protein levels, was found to be significant in a group of human melanoma cell lines (A375, G361, Hs-294T, SK-Mel-2, SK-Mel-28, and 451Lu) through real-time fluorescent quantitative PCR and Western blot analysis." (PMID 39130630, 2024). "We identified CBL mutations in patients with MM; these were risk factors for poor OS and PFS, which are infrequent in published melanoma exome studies but frequent in desmoplastic melanoma." (PMID 37649078, 2023). "The knockdown of c-CBL in melanoma cells resulted in decreased proliferation, migration, and spheroid formation." (PMID 33800394, 2021). "For example, miR-155 inhibited the proliferation, invasion, and migration of melanoma by targeting CBL." (PMID 32219065, 2020). "CBL is a tumor suppressor in the pathogenesis of human cancers, and it plays roles in melanoma cell proliferation, migration and invasion." (PMID 33231565, 2020). "We found that melanoma cells and lesional tissues exhibit c-CBL expression and its inhibition results in a decrease in proliferation, clonogenic survival, migration and invasion." (PMID 27472394, 2016). "Our findings indicate that additional studies are warranted to further dissect the role of c-CBL in melanoma and determine the therapeutic potential of its inhibition." (PMID 27472394, 2016). "Small interfering RNA (siRNA)-mediated knockdown of c-CBL resulted in decreased proliferation, clonogenic survival and migration of melanoma cells." (PMID 27472394, 2016). "In this study, we found that melanoma cell lines showed strong expression of c-CBL at both the mRNA and protein levels and strong protein expression was also present in human melanoma tissue." (PMID 27472394, 2016).